FGFR1 (fibroblast growth factor receptor 1)
Diseases named in the same sentence as FGFR1 in open-access papers (continued):
Sharing a sentence is not in itself a finding about the gene and the disease.
inflammatory skin disease (1 paper, 2020). Inflammatory skin disorders covers a broad category that includes many conditions ranging in severity, from mild itching to grave medical health complications These disorders are common in people of all ages and races. "However, the defect in the epidermal barrier and the resulting inflammatory skin disease that develops in mice lacking FGFR1 and FGFR2 in keratinocytes were further aggravated upon additional loss of FGFR3." (PMID 31830366, 2020).
influenza A (H1N1) virus infection (1 paper, 2015). "The results showed that FGFR1 phosphorylation was obviously reduced by PR8 infection over time, which suggested that influenza A (H1N1) virus infection downregulated FGFR1 phosphorylation in A549 cells." (PMID 25909503, 2015). "Our previous results suggested that influenza A (H1N1) virus infection downregulated FGFR1 expression, but whether influenza virus infection stimulated FGFR1 phosphorylation remains unknown." (PMID 25909503, 2015).
injury (1 paper, 2025). Damage inflicted on the body as the direct or indirect result of an external force, with or without disruption of structural continuity. "In acute liver injury, LESCs induce hepatocyte regeneration via CXCR7, whereas fibrosis is mediated by CXCR4 and fibroblast growth factor receptor 1 (FGFR1) in the setting of long-term injury." (PMID 40761743, 2025).
interstitial lung disease (1 paper, 2026). A diverse group of lung diseases that affect the lung parenchyma. "We demonstrate that the RET inhibitor pralsetinib (Pral) induces fatal interstitial lung disease by inhibiting FGFR1, not RET, leading to the selective loss of occludin (OCLN)." (PMID 42088419, 2026).
ischemia reperfusion injury (1 paper, 2021). Adverse functional, metabolic, or structural changes in ischemic tissues resulting from the restoration of blood flow to the tissue (reperfusion), including swelling; hemorrhage; necrosis; and damage from free radicals. "FGFR1 and FGFR2 DKO mice, which exhibit endothelial cell-specific disruption of FGF2 function, have been shown to have significantly worsened cardiac function than controls after ischemia-reperfusion injury as well as significantly decreased vessel density." (PMID 34262947, 2021).
keloid (1 paper, 2023). An irregularly shaped, elevated mark on the skin caused by deposits of excessive amounts of collagen during wound healing. "Given the close association between FGFR1 and tissue regeneration and fibrotic disease, it is reasonable to assume that FGFR1 has clinical significance in the treatment of keloids." (PMID 38137441, 2023). "To test this hypothesis, we detected the expression of FGFR1 in keloid tissue and normal skin." (PMID 38137441, 2023). "Also, derazantinib inhibited the expression of FGFR1 and PAI-1 and reduced the weight of the implanted keloid from the xenograft mice model." (PMID 38137441, 2023). "FGFR1 demonstrated higher expression in keloid tissues than in normal skin." (PMID 38137441, 2023).
Krebs 2 carcinoma (1 paper, 2022). "The obtained data confirmed the strong overexpression of Mreg, Prg4, Col3a1, Selp, Marco, and Fgfr1 genes in Krebs-2 carcinoma, as well as Cdh11, Col4a5, Vcam1, Megf6, Scarf2, Scart1, and Cd14 genes in HH47." (PMID 36555446, 2022).
leiomyoma (1 paper, 2018). A well-circumscribed benign smooth muscle neoplasm characterized by the presence of spindle cells with cigar-shaped nuclei, interlacing fascicles, and a whorled pattern. "Similar to our previous results, fibroblast growth factor receptor 1 (FGFR1) levels are lower in PTSMT as compared to leiomyomas." (PMID 29881541, 2018).
liver inflammation (1 paper, 2025). "Importantly, M2 macrophages support anti‐inflammatory responses, and experimental evidence suggests macrophage‐specific FGFR1 deletion to alleviate high‐fat‐diet‐induced liver inflammation by inhibiting MAPKs/TNF pathways." (PMID 39962359, 2025).
lobular breast carcinoma (1 paper, 2012). "In our study we found a subset of lobular breast carcinoma, be characterized by FGFR-1 amplification or gains of chromogenic signals, not only in primary tumours but also in the metastatic tissue." (PMID 23270564, 2012). "In this context, patients affected by lobular breast carcinomas and characterized by gains/amplification of FGFR-1 molecule, could receive effective regimens (predictive biomarker) with FGFR-1 inhibitors (targeted therapy)." (PMID 23270564, 2012).
lung diseases (1 paper, 2024). "The triple-angiokinase inhibitor nintedanib, which effectively blocks fibroblast growth factor receptor 1–3 (FGFR), has been investigated for lung diseases and could be considered a treatment option for BM35." (PMID 38985431, 2024).
meningioma (1 paper, 2025). A generally slow growing tumor attached to the dura mater. "Additionally, there were eight kinases that were not significantly differently expressed between meningioma and VS present in the macrophages (LCK, PDGFRB, FGFR1, FLT1, CSK, MEK, MAP2K2, and ERBB2)." (PMID 41437121, 2025).
Menorrhagia (1 paper, 2013). Prolonged and excessive menses at regular intervals in excess of 80 mL or lasting longer than 7 days. "In addition, FGFR1 up-regulation was associated with menorrhagia in UL patients." (PMID 23483937, 2013).
metastasis (1 paper, 2018). The spread or migration of cancer cells from one part of the body (where they first appeared) to another. "Especially FGFR1 (13% in PTvs.N and 7% in Mvs.PT to 10% in AMP), FGFR3 (7% in PTvs.N and Mvs.PT to 2% in AMP), DDR2 in lymph node metastasis (13% in Mvs.PT to 3% in AMP) and MET (7% in PTvs.N and Mvs.PT to 2% AMP, FC 2.4) seem to be similarly overexpressed." (PMID 29743718, 2018).
metastatic colorectal cancer (1 paper, 2017). "At the pathway level, we detected that the alteration rate (mutation and copy number variation) of the genes involved in MAPK signaling pathways, including FGFR1, FGFR2, FGFR3, FGFR4, BRAF, and MEK, was significantly lower in metastatic colorectal cancer tissue compared to the primary site." (PMID 29038591, 2017).
microcephaly (1 paper, 2022). A congenital or acquired developmental disorder in which the circumference of the head is smaller than normal for the person's age and sex. "Other common features of the FGFR1 deletion include microcephaly, growth retardation, and facial features." (PMID 35668409, 2022).
mitral valve prolapse (1 paper, 2021). A fairly common and often benign valvular heart disorder characterized by redundancy or hooding of mitral valve leaflets so that they prolapse into the left atrium, often causing mitral regurgitation. "The frameshift variant, c.2334dupC, found in a patient with vertebral segmentation defects and mitral valve prolapse, was the first FGFR1 variant to be associated with spinal malformations and heart defects." (PMID 34440300, 2021).
mucinous adenocarcinoma of the appendix (1 paper, 2023). Mucinous adenocarcinoma of the appendix is a very rare, slow growing, well-differentiated epithelial neoplasm of the appendix characterized by abundant mucin production. "In appendiceal cancers, mutations in FGFR1–3 genes are present in mucinous adenocarcinomas of the appendix." (PMID 37509254, 2023).
muscular atrophy (1 paper, 2012). The loss of muscle tissue due to inactivity or disease. "Thus, FGFR-1 and 4 downregulations in SMA-mice might fulfill negative modulating roles in myotube differentiation and muscular atrophy." (PMID 22348054, 2012).
myelocystocele (1 paper, 2023). "Thus, a terminal myelocystocele-like phenotype can arise after completion of NT closure with localised spinal mis-patterning caused by disruption of FGFR1 signalling." (PMID 37756583, 2023). "Previous studies in which Fgfr1 was deleted using TCre reported musculoskeletal phenotypes comparable with those observed here, but not PNP dysmorphology or later terminal myelocystocele-like phenotypes." (PMID 37756583, 2023).
myoepithelial carcinoma (1 paper, 2025). "In contrast, TT of FGFR1-amplified myoepithelial carcinoma with lenvatinib was unsuccessful." (PMID 41373618, 2025). "In two patients with myoepithelial carcinoma, RET p.H926L and FGFR1 amplification warranted vandetanib and lenvatinib, respectively." (PMID 41373618, 2025).
myofascial pain syndrome (1 paper, 2023). Muscular pain in numerous body regions that can be reproduced by pressure on trigger points, localized hardenings in skeletal muscle tissue. "In a rat model of myofascial pain syndrome, the protein expression levels of FGF2 and p-FGFR1 were increased and the mechanical pain threshold was decreased, suggesting a role for FGF2/FGFR1 in myofascial pain." (PMID 36845134, 2023).
myxoma (1 paper, 2023). A benign soft tissue neoplasm characterized by the presence of spindle and stellate cells, lobulated growth pattern, and myxoid stroma formation. "The bFGF and the FGFR receptors have been shown to have increased expression in the majority of myxomas, and increased microvessel density occurred in myxomas with high bFGF or FGFR-1 expression." (PMID 37197119, 2023).
nephrocalcinosis (1 paper, 2020). Nephrocalcinosis is a disorder that occurs when too much calcium is deposited in the kidneys. "The mechanism by which FGF23/FGFR1 signaling aggravates nephrocalcinosis induced by HP intake remains to be clarified." (PMID 32184468, 2020). "Our findings suggest that FGF23 is involved in nephrocalcinosis induced by HP intake partially through FGFR1 signaling." (PMID 32184468, 2020). "In the present study, FGFR1 inhibitor treatment partially recovered nephrocalcinosis induced by HP intake." (PMID 32184468, 2020). "Furthermore, FGF23 was involved in the nephrocalcinosis induced by high phosphorus intake partially through FGFR1 signaling." (PMID 32184468, 2020). "Therefore, we investigated the involvement of FGFR1 signaling in nephrocalcinosis induced by HP diet in female rats." (PMID 32184468, 2020).
neutropenia (1 paper, 2018). A decrease in the number of neutrophils found in the blood. "Notably, our study revealed that the CC genotype of FGFR1 rs2420946 significantly increased the risk of CET-induced leucopenia, neutropenia and gastrointestinal toxicity in comparison to TT genotype." (PMID 30359238, 2018).
omphalocele (1 paper, 2020). Omphalocele is an embryopathy classified in the group of abdominal celosomias and is characterized by a large hernia of the abdominal wall, centered on the umbilical cord, in which the protruding viscera are protected by a sac. "Inactivating of one copy of Fgfr1 and both copies of Fgfr2 using a global inducible Cre causes omphalocele." (PMID 32907848, 2020). "Omphalocele is also observed in Fgfr1 heterozygotes, when Fgfr2 is also conditionally inactivated at E8.5 throughout the embryo." (PMID 32907848, 2020).
osteochondrodysplasia (1 paper, 2025). A term referring to disorders characterized by abnormalities in the development of bones and cartilage. "Thus, there appears to be a dissociation between osteochondrodysplasia (driven by any variant leading to FGFR1 activation) and FGF23 excess (driven by only specific activating variants) in OGD." (PMID 41473314, 2025). "Since the osteochondrodysplasia phenotype is driven by overactivation of the FGFR1 receptor, we evaluated the effect of infigratinib, a small molecule tyrosine kinase inhibitor against FGFR1–3 activity in vitro and in vivo." (PMID 41473314, 2025).
parathyroid disease (1 paper, 2025). "Among these, several genes such as APC, CEP152, CREBBP, FAM111A, FGFR1, KL and MMP14 have been previously suggested to be associated with parathyroid disease." (PMID 40434298, 2025).
pediatric cancers (1 paper, 2025). "Using a broad search of all pediatric cancers, we observed the rates of alterations of the FGFR1, FGFR2, FGFR3, and FGFR4 genes in pediatric cancers to be 0.5%, 0.1%, 1.1%, and 0.8%, respectively." (PMID 40510032, 2025).
periampullary cancer (1 paper, 2020). "The two major findings in this study are, first, FGFR1 could be a promising prognostic marker for periampullary cancers, and second, peritumoral fibrosis was associated with tumor recurrence in periampullary cancer patients." (PMID 32171280, 2020).
peripheral nerve injury (1 paper, 2024). Injury to a peripheral nerve. "Inhibition of FGFR1 with an FGFR inhibitor has been demonstrated to reduce neuropathic pain in a rat model of peripheral nerve injury." (PMID 38638441, 2024).
pineocytoma (1 paper, 2025). "CNS_016, initially diagnosed as pineocytoma, harboured pathogenic mutations in FGFR1 and PIK3CA, alterations frequently reported in this tumour type." (PMID 41033792, 2025).
pneumonia (1 paper, 2020). An acute, acute and chronic, or chronic inflammation focally or diffusely affecting the lung parenchyma, caused by an infection in one or both of the lungs (by bacteria, viruses, fungi, or mycoplasma.). "Inhibits neuraminidase activity and influenza virus proliferation in vivo, improves pneumonia symptoms and histopathological changes, and increases the level of FGF2 and protein expression of FGFR1 in the lung." (PMID 33192523, 2020).
portal hypertension (1 paper, 2013). Increased blood pressure in the portal venous system. "It is likely that patients with a lower platelet count had more severe portal hypertension and that the vascular derangements secondary to portal hypertension lead to the decreased expression of the receptors for proangiogenic factors like FGFR1, FGFR2, and VEGFR2." (PMID 23620752, 2013).
pulmonary neuroendocrine tumors (1 paper, 2016). "High copy number gain of FGFR1 was detected in pulmonary neuroendocrine tumors." (PMID 26673008, 2016).
rectal tumor (1 paper, 2017). "Re-biopsy of the rectal tumor was obtained to assess for mechanisms of resistance and sequencing identified FGFR1 and EGFR gene amplifications; and an E1A binding protein p300 (EP300) mutation in codon L1755V, and a Wolf-Hirschhorn Syndrome Candidate 1-Like 1 (WHSC1L1) mutation in codon E123Q." (PMID 28915719, 2017). "Analysis revealed a mutation in KIT at codon G961S, PIK3CA and MYC gene amplifications that were not noted on prior testing and confirmed FGFR1 and EGFR amplifications which were previously identified in the progressed rectal tumor tissue." (PMID 28915719, 2017).
renal dysplasia (1 paper, 2012). Renal dysplasia is a form of renal malformation in which the kidney(s) are present but their development is abnormal and incomplete. "In sharp contrast, Fgfrl1 null mice have a phenotype with renal dysplasia very similar to mice with a conditional disruption of Fgf8 or a compound disruption of the two receptors Fgfr1 and Fgfr2." (PMID 22432025, 2012).
renal hypoplasia (1 paper, 2022). Renal hypoplasia is a developmental anomaly in which one or both kidneys (unilateral or bilateral renal hypoplasia, respectively) have a deficit in the number of nephrons and may be small. "The impairment of FGFR1 and FGFR2 expression suggests the involvement of the observed markers in generating the CAKUT phenotype resulting in renal hypoplasia." (PMID 35216141, 2022).
retinal degeneration (1 paper, 2017). Degeneration of the retina. "FGF2 and FGFR1 mRNA levels are greatly increased in light-induced retinal degeneration." (PMID 29312335, 2017).
retinal disease (1 paper, 2019). "FGFR-1 is expressed in human specimens of neovascular AMD and its role in retinal disease is also validated in an animal model of retinal injury." (PMID 31428180, 2019).
retinoblastoma (1 paper, 2022). A malignant tumor that originates in the nuclear layer of the retina. "Moreover, experimental evidence shows that treatment with exogenous FGF1 induces the activation and phosphorylation of FGFR1 in the human retinoblastoma Y-29 cell line, while the selective inhibition of FGFR1 resulted in decreased cell proliferation." (PMID 35409195, 2022).
Rickettsia infection (1 paper, 2017). "Our results imply that FGFR1 likely interacts with caveolin-1, because Rickettsia infection enhances the association of these proteins." (PMID 28806774, 2017).
secondary hyperparathyroidism (1 paper, 2016). Overproduction of parathyroid hormone in response to influence external to the parathyroid glands. "Indeed, conditional deletion of FGFR1 in the distal tubule resulted in a marked increase in urinary excretion of calcium that was severe enough to cause secondary hyperparathyroidism." (PMID 26839958, 2016).
silicosis (1 paper, 2020). Silicosis is a respiratory disease caused by breathing in (inhaling) silica dust. "Further researches in vivo will be necessary to clarify the precise regulation of VEGFA and FGFR1 by miR‐503 in silicosis." (PMID 33135394, 2020). "Besides, we found that the protein expression levels of VEGFA and FGFR1 were significantly up‐regulated in the lung tissues of silica‐treated mice, and overexpression of miR‐503 in a mouse model of silicosis efficiently suppressed these two targets." (PMID 33135394, 2020).
skin hemangioma (1 paper, 2017). A hemangioma arising from the skin. "To confirm this statement and explore the relationship between miR-424 and FGFR1, we examined the FGFR1 expression in infant skin hemangioma tissues using immunohistochemistry." (PMID 28928430, 2017). "Our results showed that miR-424 expressed at low levels in infantile skin hemangioma tissues and was negatively correlated with the expression of FGFR1; miR-424 overexpression downregulated the expression of FGFR1 in HemECs, while miR-424 inhibition upregulated FGFR1 expression." (PMID 28928430, 2017). "Our results indicated that miR-424 suppressed the bFGF/FGFR1 pathway by targeting FGFR1, thereby inhibiting ERK1/2 phosphorylation, and thus inhibiting cell proliferation, migration and tube formation and the development of infantile skin hemangioma." (PMID 28928430, 2017). "Based on the staining intensity, FGFR1 expression was divided into four levels (0, 1, 2 and 3): 0, negative expression of FGFR1 in infantile skin hemangioma tissues; 1, weakly positive expression of FGFR1; 2, moderately positive expression of FGFR1; and 3, strongly positive expression of FGFR1." (PMID 28928430, 2017). "In conclusion, miR-424 could suppress the bFGF/FGFR1 pathway, thereby inhibit ERK1/2 phosphorylation, and thus inhibit cell proliferation, migration and tube formation capabilities and the development of infantile skin hemangioma." (PMID 28928430, 2017). "Our study indicated that miR-424 may reduce FGFR1 expression, suppress the bFGF/FGFR1 pathway, thereby inhibit ERK1/2 phosphorylation, and thus inhibit the cell proliferation, migration and tube formation capabilities and the development of infantile skin hemangioma." (PMID 28928430, 2017).
solitary fibrous tumor (1 paper, 2024). Solitary fibrous tumor (SFT) represents a diverse group of ubiquitous rare spindle cell neoplasms that may be benign or malignant and that most frequently arises from the pleura and peritoneum and rarely from other sites such as head and neck, liver and skeletal muscle. "Overexpression of IGF2 related to LOI and receptor tyrosine kinase genes including DDR1, ERBB2, and FGFR1 have implicated the IGF2-INSR pathway in sphere formation of solitary fibrous tumor (SFT)." (PMID 38812777, 2024).
Ta (1 paper, 2024). "Our analysis identified two subgroups in Ta tumors: one with FGFR3 alterations linked to LG tumors and favorable outcomes, and another with alterations in ERBB2, PIK3CA, and ERBB3 mutations, and FGFR1, CCND1, and MYC amplifications, associated mostly with HG tumors and poorer prognosis." (PMID 39410541, 2024).